IL2 (interleukin 2)
Diseases named in the same sentence as IL2 in open-access papers (continued):
Sharing a sentence is not in itself a finding about the gene and the disease.
Zinc deficiency (28 papers, 2009 to 2025). A deficiency of the essential metal Zinc; an essential cofactor for many enzymes. "It was previously reported that zinc deficiency led to decreased expression of IL‐2 caused by the reduced activating effect of zinc on NFκB pathway." (PMID 40605399, 2025). "In conclusion, we identified CREM 100 kDa as a potential molecular mechanism behind the lead-induced IL-2 decrease in Jurkat T cells, with zinc deficiency exacerbating this effect." (PMID 39796118, 2024). "Zinc deficiency enhanced and zinc supplementation reduced the IL-2 decrease and CREM 100 kDa increase." (PMID 39796118, 2024). "We show that zinc deficiency amplifies and zinc supplementation can prevent the lead-induced IL-2 decrease and CREM 100 kDa increase." (PMID 39796118, 2024). "In zinc deficiency, IL-2 production is decreased, while zinc supplementation in zinc-deficient elderly or zinc-deficient patients improves IL-2 expression." (PMID 39796118, 2024). "The combination of zinc deficiency and lead exposure further reduced IL-2 and increased CREM 100 kDa." (PMID 39796118, 2024). "Consistently, another study demonstrated that zinc deficiency reduced the production of interferon-gamma, interleukin-2 (IL-2), and tumor necrosis factor-alpha (TNF-α)." (PMID 37049478, 2023). "Recent studies by our group have shown that zinc deficiency leads to reduced IL-2 transcription and secretion by increasing the expression of CREMα, a negative regulator of IL-2 transcription." (PMID 36674704, 2023). "In the present report, we first evaluated the existence of a distinctive molecular mechanism of zinc deficiency-triggered IL-2 suppression in human peripheral blood mononuclear cells (PBMC)." (PMID 36042501, 2022). "In parallel, studies uncovered the transcription factor cAMP-responsive element modulator alpha (CREMα) to be upregulated due to zinc deficiency, leading to dampened IL-2 production." (PMID 36551176, 2022). "Zinc deficiency, on the other hand, decreased NK-cell activity and dampened the IL-2 medication’s boosting impact on NK cells." (PMID 36213442, 2022). "Zinc deficiency in mammals can adversely affect Th1 type immune response and IL-2 production and apoptosis." (PMID 32872199, 2020). "Zinc deficiency also seems to decrease natural killer (NK) cells and thus their cytotoxic effects and the production of IL-2, which is responsible for the activation of T cells and stimulation of NK proliferation." (PMID 33375344, 2020). "In an experimental model of human mild zinc deficiency, we reported decreased thymulin (a thymopoietic hormone) activity in Th1 cells, decreased mRNAs of IL-2 and IFN-gamma genes, and decreased activity of natural killer cells (NK) and T cytotoxic T cells." (PMID 32411807, 2020). "Quantitative analysis of the alkaline phosphatase activity of granulocytes, plasma thymulin, and IL-2 expression in mononuclear cells are also effective diagnostic tests to assess zinc deficiency." (PMID 31035445, 2019). "Zinc deficiency not only affects adversely the thymulin (a thymic hormone) activity but also decreases the generation of IL-2 and IFN-γ from Th1 cells." (PMID 25988117, 2014). "Zinc deficiency influences the generation of cytokines, including IL-1β, IL-2, IL-6, and TNF-α, and in response to zinc supplementation plasma cytokines exhibit a dose-dependent response." (PMID 22852057, 2012). "In cases of zinc deficiency, even short-term supplementation of in average 6 days can significantly improve immune function by decreasing CREMα expression and thereby increasing IL-2 production." (PMID 40390089, 2025). "It was described that zinc deficiency in Jurkat T cells led to decreased IL‐2 expression." (PMID 40605399, 2025). "Moreover, zinc deficiency alters cytokine-mediated signaling, enhancing B cell proliferation in response to IL-6 and IL-2 but reducing it following IL-4 stimulation." (PMID 40390089, 2025).
Zinc deficiency (continued). "Consequently, IL-2 production was significantly lower in cells exposed to both lead and zinc deficiency compared to lead exposure alone." (PMID 39796118, 2024). "The combination of lead exposure and zinc deficiency decreased IL-2 production even further." (PMID 39796118, 2024). "Moreover, we presume that the co-occurrence of zinc deficiency and lead exposure will result in a further reduction in IL-2 production due to CREM expression being upregulated." (PMID 39796118, 2024). "Similarly, zinc deficiency adversely affects T cells, with zinc deficiency and lead exposure being linked to reduced interleukin-2 (IL-2) production." (PMID 39796118, 2024). "Zinc deficiency leads to a dysregulation of interleukin-10 (IL)-10, IL-2, and IFN-γ production." (PMID 36678229, 2023). "We published later that the assay of IL-2 mRNA may be a specific and sensitive biomarker of human zinc deficiency." (PMID 32411807, 2020). "The effect of zinc deficiency on thymulin activity and IL-2 mRNA was seen within eight to twelve weeks of the institution of zinc-deficient diet in human volunteers, whereas lymphocyte zinc decreased in 20 weeks and plasma zinc decreased in 24 weeks after instituting zinc-deficient diet." (PMID 32411807, 2020). "For example, zinc deficiency was found to decrease the expression and production of interleukin-2 (IL-2) and IL-2 receptors as well as interferon γ (IFN-γ) cytokines in HUT-78 cells (a type of Th0 malignant lymphomatoid cell), as compared to zinc-sufficient cells." (PMID 31174269, 2019). "In our experience, determination of zinc in the lymphocytes, plasma somatomedin activity, and measurement of IL-2 mRNA in PHA stimulated mononuclear cells by reverse transcriptase (RT)-polymerase chain reaction (PCR) are the most sensitive tests for diagnosing zinc deficiency in humans." (PMID 25988117, 2014). "Hence, a thorough understanding of the molecular mechanisms underlying the zinc deficiency-induced IL-2 production impairment may help unravel important immune aging principles and develop potential health-promoting strategies." (PMID 36042501, 2022). "Zinc deficiency activates NF-κB factor and it adversely affects thymulin activity, growth, and functioning of T- and B-lymphocytes, phagocytosis and cytokine production, as well as gene expression of IL-2 and its receptors, resulting in the drastic reduction of organism’s resistance to infection." (PMID 31035445, 2019). "Zinc deficiency has been shown to decrease the production of TNF-α, IFN-γ and IL-2 by peripheral blood mononuclear cells." (PMID 40072975, 2025). "Conversely, zinc deficiency shifts the immune response further towards a Th2-dominant profile, going along with the reduction of Th1 cell cytokines, such as IFN-γ, IL-2 and TNF-α." (PMID 40390089, 2025). "Zinc deficiency has been associated with increased expression of the transcription factor CREM 100 kDa, which downregulates IL-2." (PMID 39796118, 2024). "In order to investigate the reduced expression of IL-2 in the PPI-treated PBMC, we examined CREMα, which has been shown to inhibit IL-2 transcription in zinc deficiency." (PMID 36674704, 2023). "Serum changes associated with zinc deficiency also include an increase in Tumor Necrosis Factor-alpha (TNF-a) and pro-inflammatory cytokines and a decrease in anti-inflammatory cytokines such as interleukin-2 (IL-2) and interleukin-4 (IL-4)." (PMID 35353297, 2022). "During zinc deficiency, studies reported an imbalance between Th1 and Th2 cell differentiation, resulting in a diminished Th1 immune response with lowered IFN-γ and IL-2 production, whereas the Th2 cytokines (IL-4, IL-6, and IL-10) remain unaffected." (PMID 36551176, 2022). "A large category of cytokines, including IL-4, IL-6, interferon-g (IFN-g), TNF-α from innate immunity, and IL-2, TNF, and IFN-γ from adaptive immunity were found to be inhibited in production in patients with zinc deficiency." (PMID 35211497, 2022).
Zinc deficiency (continued). "Zinc deficiency also decreases the production of Th1 cytokines (TNF-α, IL-2, and IFN-γ), whereas the Th2 cytokine response (IL-10, IL-6, and IL-4) is less affected." (PMID 32944394, 2020). "Zinc was also required for gene expression of IL-2 and IFN-γ from Th1 cells, and the generation of these cytokines was adversely affected due to zinc deficiency." (PMID 32411807, 2020). "For instance, zinc deficiency reduced production of Th1 cytokines, in particular IFN-γ, IL-2, and tumor necrosis factor (TNF)-α, whereas levels of Th2 cytokines IL-4, IL-6, and IL-10 were not affected." (PMID 29196724, 2017). "The generation of a variety of cytokines, including IL-1β, IL-2, IL-6, and TNF-α, is reportedly influenced by mild to moderate zinc deficiency in humans." (PMID 22852057, 2012). "When zinc deficiency was experimentally induced in young subjects, they showed significant effects on the production of IFN-γ, IL-2, and TNF-α with an imbalance in the TH1/TH2 system, but plasma zinc was not significantly affected." (PMID 19523191, 2009). "During zinc deficiency, the production of TH1 cytokines, in particular IFN-γ, IL-2, and tumor necrosis factor (TNF)-α is reduced, whereas the levels of the TH2 cytokines IL-4, IL-6, and IL-10 were not affected in cell culture models and in vivo." (PMID 19523191, 2009). "In zinc-deficient elderly patients, zinc supplementation reverses the negative effect of zinc deficiency, leading to low CREMα expression and thus normal IL-2 transcription." (PMID 36674704, 2023). "Nevertheless, the molecular mechanisms underlying a zinc deficiency-induced decrease in IL-2 production have not yet been satisfactorily elucidated." (PMID 36042501, 2022). "Serum thymulin activity, IL-2 mRNA generation after PHA-PMA activation of peripheral blood mononuclear cells, and assay of activity of ecto-5′NT, a marker for lymphocyte maturity, are more sensitive biomarkers of zinc deficiency in comparison to the assay of zinc in plasma or peripheral blood cells." (PMID 32411807, 2020). "In humans, Zinc deficiency has been reported to cause an imbalance between Th1 and Th2 cells: the Th1 function is decreased, while Th2 function is not affected, with increase in the production of IFNγ, IL-2, and tumour necrosis factor α (TNFα)." (PMID 27143960, 2016).
Cognitive impairment (27 papers, 2016 to 2025). Abnormal cognition is characterized by deficits in thinking, reasoning, or remembering. "It has been reported that CREB dysfunction in the hippocampus, through the downregulation of interleukin-2, causes cognitive deficits and depressive-like behaviors in mice." (PMID 41204270, 2025). "IL‐2 was negatively associated with anxious symptoms (p = .00), and IL‐2 was also significantly positively correlated with cognitive impairment (p = .00)." (PMID 32790154, 2020). "Cognitive impairment seems to be the result of IL-2-enhanced production (which is associated with hippocampal neuronal loss and prevention of long-term potentiation in rats), whereas a relative hyperdopaminergic state underlies the interferon-associated psychotic symptoms." (PMID 34945228, 2021). "Animal studies support that peripheral IL-2 administration can induce fatigue-like behaviour and cognitive deficits, possibly via cytokine-induced sickness behaviour mechanisms." (PMID 41057909, 2025). "Of interest, patients with mild cognitive impairment who developed postoperative delirium presented higher plasma levels of IL-2 and cortisol." (PMID 39860413, 2025). "Early-stage depletion of regulatory CD4+ T cells in AD mouse models has been shown to worsen cognitive deficits, while enhancing their numbers with treatments like IL-2 can improve cognitive function and reduce Aβ plaque load." (PMID 38658964, 2024). "Daytime changes were positively correlated with IL-2 (r = 0.462, P = 0.030), IL-6 (r = 0.516, P = 0.017), and IL-8 (r = 0.462, P = 0.030) levels, and there was a positive correlation between cognitive disorder scores and IL-6 levels (r = 0.492, P = 0.023)." (PMID 38877455, 2024). "Studies have shown that early transient depletion of Tregs accelerate cognitive impairment and amplification of Tregs through peripheral IL-2 treatment restored cognitive function in APP/PS1 mice." (PMID 38023614, 2023). "Greater severity of cognitive impairment measured using the ACE-R and the MMSE was associated with having a significantly lower level of IL-1beta, IL-2 and IL-4, and a higher level of IL-6 and TNF-alpha." (PMID 29248892, 2018). "Node betweenness was the highest for perceived cognitive impairment and the IL-2 level." (PMID 40633921, 2025). "Our previous studies have shown that plasma pro-inflammatory cytokines/cytokines, particularly RANTES, IP-10, and IL-2, were strong correlates of HIV- associated cognitive impairment and have shown significant clinical validity as candidates for HAND diagnosis." (PMID 41465427, 2025). "Cognitive impairment is often described as an element of the so-called sickness behavior characterized by an increase in cytokines such as interleukin 1 (IL-1), interleukin 2 (IL-2), or tumor necrosis factor alpha (TNF-α)." (PMID 31044590, 2019). "Changes in the blood-cerebrospinal fluid barrier found in patients with mild cognitive impairment may facilitate the entry of systemic IL-2 into the nervous system." (PMID 31697701, 2019). "Worsening cognitive impairment was correlated with a decrease in the cytokines IFN-γ, IL-1β, IL-2, IL-4, and IL-10." (PMID 37569491, 2023). "Blood studies showed that higher levels of pro-inflammatory markers were linked with a more severe motor phenotype (IFN-γ, TNF-α, IL-2, and IL-10), faster motor progression (CRP and IL-6), cognitive impairment (IFN-γ, TNF-α, IL-2, and IL-10), and worse sleep quality (CRP)." (PMID 36337703, 2022). "IL-2 level is closely related to negative symptoms and cognitive deficit and is also varied after treatment." (PMID 36138890, 2022).
Sjögren’s syndrome (27 papers, 2006 to 2025). "The lymphocytes in the salivary glands have been shown to produce IL-226 and IL-2 treatment has been shown to improve salivary secretions in a mouse model of Sjogren's syndrome, suggesting that Covid-19 could damage the salivary glands causing lower levels of salivary IL-2 and reduced salivary flow." (PMID 36846089, 2023). "In individuals with primary Sjogren’s syndrome (an chronic inflammatory autoimmune disease), interleukin-2 was positively correlated with LDL-C (r = 0.7, P = 0.02)." (PMID 40166678, 2025). "This study investigates the metabolic effects of Ld-IL2 therapy in patients with primary Sjögren’s syndrome (pSS)." (PMID 39482484, 2024). "Among transcription factors activated by the IL-2 signalling pathway belongs STAT5 with differing level of phosphorylation observed in peripheral blood cells of Sjögren’s syndrome patients." (PMID 37353767, 2023). "Fas/FasL and IL-2Rα/IL-2 correlate with severity of Sjögren’s syndrome and the efficacy of its treatment Anti-inflammatory drugs (NSAIDs) can interfere with proliferation and apoptosis via several mechanisms." (PMID 37353767, 2023). "Non-obese diabetic/Ltj (NOD) mice were used as the animal model of Sjögren’s syndrome, and low-dose IL-2 or phosphate buffered saline was administered subcutaneously from 5 weeks of age, while ICR mice were used as controls." (PMID 36244973, 2022). "The aim of this study was to investigate the effects of low-dose IL-2 on salivary gland structure and function in a murine model of Sjögren’s syndrome." (PMID 36244973, 2022). "The study aimed to quantify certain cytokines involved in the pathomechanism of primary Sjögren syndrome (IL2, IL5, IL6, IL10, IL13, TNFα, IFNγ) and determine their common clinical correlation." (PMID 36143051, 2022). "This randomized clinical trial investigates the efficacy, safety, and immune response of low-dose interleukin 2 in the treatment of primary Sjögren syndrome." (PMID 36355371, 2022). "Their response on IL-2 stimulation differs in Sjögren’s syndrome patients." (PMID 37353767, 2023). "In Sjögren’s syndrome, unusual expression of IL-2/(s)IL-2Rα has been also described." (PMID 37353767, 2023). "Effects of low-dose interleukin-2 (IL-2) on the exocrine glandular glands of Sjögren’s syndrome are unknown." (PMID 36244973, 2022). "Is low-dose interleukin 2 (LD-IL-2) effective in the treatment of primary Sjögren syndrome (pSS)?" (PMID 36355371, 2022). "Furthermore, a disruption of IL-2 signalling in CD25 knock-out mice resulted in age-dependent Sjögren’s syndrome-like autoimmune lacrimal-keratoconjunctivitis." (PMID 35526080, 2022). "Interestingly, we observed that patients with thyroid autoimmune diseases (i.e., Graves’ disease or Hashimoto thyroiditis) may show 99mTc-IL2 uptake in the salivary glands, predicting the development of a secondary Sjögren’s syndrome in the following years." (PMID 35955984, 2022). "An earlier report suggested that mRNA expression of Th1 and derived inflammatory cytokines IL-2, TNF-α, and INF-γ were also increased in the saliva of the patients with Sjögren’s syndrome." (PMID 32164227, 2020). "In Sjögren's syndrome there are increased levels of inflammatory mediators (PGE2, thromboxane B2, IL-2 and IL-6) in saliva, which can assist in the diagnosis." (PMID 18221457, 2008). "Our results demonstrate that treatment with low-dose IL-2 improves the secretory function of the exocrine glands of mice with Sjögren’s syndrome, but it does not reverse the structural damage of the exocrine glands." (PMID 36244973, 2022). "Additionally, our study focused on the effects of low-dose interleukin 2 therapy alone without considering potential interactions with other treatments commonly used in patients with primary Sjögren's Syndrome." (PMID 39482484, 2024).